DCT (dopachrome tautomerase)
Diseases named in the same sentence as DCT in open-access papers (continued):
Sharing a sentence is not in itself a finding about the gene and the disease.
vitiligo (11 papers, 2012 to 2024). Generalized well circumscribed patches of leukoderma that are generally distributed over symmetric body locations and is due to autoimmune destruction of melanocytes. "TYR, TYRP1, Dopachrome Tautomerase (DCT), La-ribonucleoprotein-7 (LARP7), and Kinesin Family Member 1A (KIF1A) were identified as candidate biomarkers for vitiligo with associated immune infiltration." (PMID 38666916, 2024). "As expected, the expression of MC1R, TYR, TYRP1, and DCT was significantly downregulated during vitiligo pathogenesis." (PMID 38159176, 2024). "Ultimately, TYR, TYRP1, DCT, and LARP7 have been screened as candidate biomarkers associated with vitiligo." (PMID 34107850, 2021). "Both vitiligo associated genes (PMEL, TYRP1, DCT & MLANA) and PD-L1 had mRNA levels near the median value observed across the dataset." (PMID 30832716, 2019). "TYR, TYRP1, DCT, and LARP7 were selected as biomarkers associated with vitiligo." (PMID 34107850, 2021). "In summary, we found that TYR, TYRP1, DCT, and LARP7 are biomarkers associated with vitiligo." (PMID 34107850, 2021). "Previous studies have reported that melanocyte signal pathway is one of the core signal pathways in vitiligo, dominating melanocyte production, destruction, and pigment transport as transcription factors of melanocyte signal pathway, TYR, TYRP1, and DCT involved in vitiligo progression." (PMID 34107850, 2021). "Herein, TYR, TYRP1, DCT, and LARP7 were chosen as biomarkers to identify vitiligo by combining machine learning algorithm and WGCNA." (PMID 34107850, 2021). "TYR, TYRP1, TYRP2, and DCT mRNA levels in vitiligo patients are significantly downregulated and can lead to decreased melanin synthesis." (PMID 34107850, 2021). "Similarly, in vitiligo, CD8+ T cells target antigens from melanosomal proteins such as PMEL, MLANA/MART1, TYR, TYRP1, and DCT." (PMID 37339630, 2023). "TYR, TYRP1, DCT and LARP7 were identified as vitiligo-related biomarkers." (PMID 34107850, 2021). "TYR, TYRP1, DCT, and LARP7 were involved in the pathogenesis of vitiligo." (PMID 34107850, 2021). "Moreover, DCT, TYR, EDNRB and TYRP1 have also been reported previously playing a vital role in vitiligo." (PMID 32509450, 2020). "Therefore, other differential genes which were enriched along with WNT6, DCT, TYR, EDNRB and TYRP1 by GO could provide more insights on vitiligo prognosis." (PMID 32509450, 2020).
metastatic melanoma (8 papers, 2011 to 2024). A melanoma that has spread from its primary site to another anatomic site. "In this context, a previous study using cDNA microarray analysis showed that high expression of DCT/TYRP2 in metastatic melanoma was associated with a shorter patient survival." (PMID 22045183, 2011). "TRP-2 is a DOPAchrome tautomerase and its overexpression is believed to contribute to the chemoresistance and radiotherapy resistance of metastatic melanoma." (PMID 29276510, 2017).
albinism (5 papers, 2022 to 2023). A congenital disorder characterized by partial or complete absence of melanin pigment in the eyes, hair, or skin. "Recently, the new mutations in the TYRP2 gene (also known as the DCT gene), involved in albinism, were identified in the genetic study." (PMID 35163231, 2022). "(2021) reported how mutations in l‐dopachrome tautomerase (DCT), a key enzyme in melanin synthesis, can produce variable phenotypes resembling either IIN or albinism." (PMID 35616929, 2022). "Molecular studies identified seven genes linked to the OCA phenotype (TYR, OCA2, TYRP1, SLC45A2, SLC24A5, C10orf11, and DCT) and one locus (OCA5) in consanguineous and sporadic albinism." (PMID 35741834, 2022).
glioma (4 papers, 2010 to 2023). A benign or malignant brain and spinal cord tumor that arises from glial cells (astrocytes, oligodendrocytes, ependymal cells). "However, we and others have observed that anti-tumor T cells in DC-vaccinated human and mouse glioma hosts predominantly recognize Trp-2, or dopachrome tautamerase (DCT;), which has been shown to enhancee stem-like properties in neural progenitors." (PMID 20539758, 2010).
cutaneous melanoma (3 papers, 2016 to 2022). A primary melanoma arising from atypical melanocytes in the skin. "In the Tg(Grm1) model, the Dopachrome tautomerase (Dct) promoter controls expression of the metabotropic glutamate receptor to produce both uveal melanoma and cutaneous melanoma." (PMID 31880399, 2020). "According to the pan-cancer study of the GEPIA database, DCT was highly expressed in skin cutaneous melanoma (SKCM) and almost not expressed in normal skin tissues and other tissues." (PMID 35096060, 2022).
melasma (3 papers, 2013 to 2025). "Sanger sequencing of pharyngeal swabs from 80 patients with melasma combined with genomic association analysis showed that TYR and DCT were the relevant genetic loci for melasma." (PMID 40369904, 2025). "The potential mechanism of PE extract against melasma was predicted to target the CREB1/MITF/TYR/DCT axis." (PMID 40369904, 2025). "In this study, Sanger sequencing of pharyngeal swabs from melasma populations and genomic association analysis revealed that TYR and DCT were the relevant genetic loci for melasma." (PMID 40369904, 2025). "DNA sequencing revealed that TYR and DCT were genes related to melasma." (PMID 40369904, 2025). "Furthermore, CTNNB1 was linked to genes like DCT and HMGCS1, which were related to melanin biosynthetic process and lipid metabolic process reported in melasma study." (PMID 34609489, 2022). "Pearl can alleviate melasma by targeting the CREB1/MITF axis and then the melasma‐related gene loci TYR and DCT." (PMID 40369904, 2025). "Here, we found that MITF overexpression can reverse the effects of pearl in melasma, suggesting the involvement of the MITF/TYR/DCT axis in the antimelasma mechanism of pearl." (PMID 40369904, 2025).
breast carcinoma (2 papers, 2017 to 2018). "For instance, PHTF1, MUC5AC, ZNF192, PCSK6, and HDGFRP3 are shown to be involved in breast cancer, and some common genes such as DCT, ZP2, and CEACAM7 might be involved in breast cancer." (PMID 29589558, 2018). "Furthermore, DCT and ZP2 are high-profile biomarkers, and their role in breast cancer requires further investigation." (PMID 29589558, 2018).
oculocutaneous albinism (2 papers, 2022 to 2023). Oculocutaneous albinism (OCA) describes a group of inherited disorders of melanin biosynthesis characterized by a generalized reduction in pigmentation of hair, skin and eyes and variable ocular findings including nystagmus, reduced visual acuity and photophobia. "We have recently identified DCT encoding dopachrome tautomerase (DCT) as the eighth gene for oculocutaneous albinism (OCA)." (PMID 35885947, 2022).
psoriasis (2 papers, 2021 to 2025). An autoimmune condition characterized by red, well-delineated plaques with silvery scales that are usually on the extensor surfaces and scalp. "To conclude, this study showed the associations between MC1R and DCT polymorphisms and psoriasis in the Tatar population, suggesting that these genetic variants may contribute to a predisposition to psoriasis." (PMID 40650250, 2025). "This may result from elevated proinflammatory cytokines in psoriasis-TNF, IL-17, IL-1 and IL-6, which are known to inhibit melanogenesis and specifically PKA, MITF, TYR and DCT." (PMID 34884858, 2021).
leiomyosarcoma (1 paper, 2024). An uncommon, aggressive malignant smooth muscle neoplasm, usually occurring in post-menopausal women. "The most overexpressed and underexpressed genes in CP0024 leiomyosarcoma cell cultures transduced with shHMGA1 were DCT (logFC = 1.607; adjusted p-value < 0.001), and MAGEC2 (logFC = − 2.091; adjusted p-value < 0.001), respectively." (PMID 38758230, 2024).
measles (1 paper, 2020). A highly contagious viral infection caused by the measles virus. "Using ovalbumin (OVA) and tyrosinase-related protein-2 (TRP-2, synonym L-dopachrome tautomerase) as model antigens, we demonstrate activation of cognate CTLs by recombinant measles vaccine vectors." (PMID 32098134, 2020).
Obesity (1 paper, 2021). Accumulation of substantial excess body fat. "The melanocortin pathway which is linked to both melanin synthesis and obesity seems to be altered with unclear significance, as the sex difference in POMC, DCT/TYRP2, and MRAP2 was observed but with no clear direction." (PMID 34436011, 2021).
Type 1 Diabetes (1 paper, 2024). "Additionally, the DCT gene has been linked with the gut microbiota through the melatonin pathway, and the expression of SMAD9 has been linked to Bacteroides dorei in the context of Type 1 Diabetes." (PMID 38892420, 2024).
tumor (67 papers, 2006 to 2026). "To do so, we primed tumor-bearing animals with Ad-DCT and boosted the immune response 7 days later using VV, VSV or MRB together with DCT peptide (see treatment schedule)." (PMID 33976179, 2021). "For example, studies have shown that VSV-expressing tumor antigens human papilloma virus oncogene E7 (VSV-E7) and human dopachrome tautomerase (VSV-hDCT) can induce tumor antigen-specific CD8 cytotoxic T cell responses." (PMID 28751892, 2017). "The proportion of DCT-specific T cells is not reduced relative to the global number, but the remaining DCT-specific T cells are dysfunctional in their ability to secrete IFNγ in response to tumor antigen." (PMID 27196057, 2016). "As previous studies have demonstrated, Ad-DCT is able to prime a DCT specific T cell immune response and protect mice from a B16 tumor challenge or tumor re-growth, but has limited efficacy in a therapeutic model of lung metastases." (PMID 25161958, 2014). "Both hyper- and hypo-pigmented tumors are enriched in melanocytes as revealed by EM analysis of tumor samples and in situ hybridization on cryostat section for dopachrome tautomerase (dct, a marker of melanin biosynthetic pathway)." (PMID 21170325, 2010). "DCT was shown to interact with components of the tumour microenvironment, affecting not just the cancer cells but also the immune response and the surrounding tissue." (PMID 41465475, 2025). "Moreover, well-known target proteins of MITF in melanogenesis such as TYRP1, DCT, and TYR1 proteins were positivity regulated in Opn4WT tumor, and therefore, strongly suggest a reduction of MITF signaling in Opn4KO tumor." (PMID 35562405, 2022). "Moreover, DCT is not expressed in amelanotic form of the tumour." (PMID 41465475, 2025).
cancer (14 papers, 2015 to 2025). A tumor composed of atypical neoplastic, often pleomorphic cells that invade other tissues. "To proof the concept of using the meprin α tail for expression and solubilization of other membrane bound proteins, we also tested this strategy for the cancer related tyrosinase TRP-2 (UniProtKB P40126, TRP2_HUMAN, tyrosinase related protein 2, DOPAchrome tautomerase)." (PMID 27054568, 2016).
infection (1 paper, 2017). The state of being infected such as from the introduction of a foreign agent such as serum, vaccine, antigenic substance or organism. "We observed increased viral DNA localization at the endoplasmic reticulum but an overall decrease in infection in DCT knockdown cells." (PMID 28095444, 2017). "For the rest of the study, we investigated the mechanism of decrease in infection in DCT knockdown cells." (PMID 28095444, 2017). "HPV16 PsVs were found to localize to early endosomes at 4 hours post infection (hpi) at comparable levels in DCT knockdown and control cells as detected by the overlap of the green (EEA1) and red (H16.V5) signal." (PMID 28095444, 2017). "In our experiments, we observed increased viral DNA localization at the ER but an overall decrease in infection in DCT knockdown cells." (PMID 28095444, 2017). "However, further studies are needed to assess whether a higher-efficiency DCT knockdown would alter cell cycle in a more drastic way or whether antioxidant treatments can rescue infection in DCT knockdown cells." (PMID 28095444, 2017). "Although ER trafficking was not impaired, infection in in DCT knockdown cells was either significantly decreased compared to the control cells or completely inhibited in the case of XXI treated cells." (PMID 28095444, 2017). "Furthermore, we suggest that in the absence of DCT, increased ROS and DNA damage affect cell cycle progression, which hinders viral DNA’s egress from ER and localization to nucleus—an event required for successful infection." (PMID 28095444, 2017).
DCT also shares sentences with these, for which no sentence is quoted: glioblastoma (2 papers); Autoimmunity (1); ciliopathy (1); colon carcinoma (1); eosinophilia (1); Genetic Disorders (1); Hashimoto thyroiditis (1); hepatocellular carcinoma (1); Hypomagnesemia (1); lung carcinoma (1); microphthalmia (1); neuroblastoma (1); nevus (1); ocular melanoma (1); ocular melanosis (1); oculocutaneous albinism type 8 (1); ovarian carcinoma (1); retinoblastoma (1); skin cancer (1); squamous cell carcinoma (1).